OTUD3 (OTU deubiquitinase 3)
Diseases named in the same sentence as OTUD3 in open-access papers (continued):
Sharing a sentence is not in itself a finding about the gene and the disease.
glioma (4 papers, 2023 to 2025). A benign or malignant brain and spinal cord tumor that arises from glial cells (astrocytes, oligodendrocytes, ependymal cells). "For example, OTUD3 promotes the progression of PTEN-associated glioma." (PMID 38429268, 2024). "Studies have also reported that OTUD3 is lowly expressed in glioma, colorectal, cervical, and thyroid cancers, correlating with their poor prognosis, and OTUD3 also appears to inhibit cancer cell proliferation and metastasis by stabilizing PTEN proteins." (PMID 41050073, 2025). "PTEN and OTUD3 protein expression was significantly lower in C6 cells compared to primary astrocytes, and survival time was longer in patients with high OTUD3-expressing gliomas than in patients with low-expressing gliomas." (PMID 37829187, 2023). "It was concluded only that the low expression of OTUD3 in glioma cells may be involved in gliomagenesis, but the mechanism behind this is unclear." (PMID 37829187, 2023). "Lower expression in gliomas suggests involvement in gliomagenesis, while OTUD3 locus deletion may contribute to squamous cell carcinoma." (PMID 38288086, 2023). "OTUD3 shows varied effects in gliomas and squamous cell carcinomas." (PMID 38288086, 2023).
liver cancer (3 papers, 2019 to 2025). An epithelial or non-epithelial malignant neoplasm that arises from the liver. "The results demonstrated that liver cancer patients with high OTUD3 expression had a markedly poorer overall survival probability than those with low OTUD3 expression." (PMID 34380780, 2021).
lung adenocarcinoma (3 papers, 2019 to 2024). A carcinoma that arises from the lung and is characterized by the presence of malignant glandular epithelial cells. "Mechanistically, OTUD3 promotes the proliferation of lung adenocarcinoma through deubiquitylation and stabilization of GRP78." (PMID 38539203, 2024). "Mechanistically, OTUD3 promotes tumorigenesis of the lung adenocarcinoma through deubiquitylating and stabilizing GRP78." (PMID 31266968, 2019). "In contrast, in lung adenocarcinoma, the expression level of OTUD3 was increased as compared with the matched adjacent normal tissues and it was irrelevant with the expression of PTEN, whose expression was reduced in lung adenocarcinoma." (PMID 31266968, 2019). "Notably, OTUD3 functions as a tumor promoter in the lung adenocarcinoma in vivo instead of a tumor suppressor." (PMID 31266968, 2019). "OTUD3 can also be ubiquitinated by TRIM56, thereby inhibiting invasion and migration of lung adenocarcinoma." (PMID 37829187, 2023).
non-small cell lung carcinoma (3 papers, 2023). A group of at least three distinct histological types of lung cancer, including non-small cell squamous cell carcinoma, adenocarcinoma, and large cell carcinoma. "A small molecule OTUD3 inhibitor named OTUDin3 has been reported for the treatment of non-small cell lung cancer." (PMID 37829187, 2023). "For example, high mRNA expression levels of OTUD1, OTUD3, OTUD4, and ALG13 are associated with improved prognosis in non-small cell lung cancer (NSCLC) and adenocarcinoma, but not in squamous cell carcinoma." (PMID 36829909, 2023).
Obesity (3 papers, 2022 to 2023). Accumulation of substantial excess body fat. "Otud3−/− mice show a significant impairment of energy metabolism and are susceptible to obesity and metabolic disorders." (PMID 37829187, 2023).
Parkinson disease (3 papers, 2022 to 2025). A progressive degenerative disorder of the central nervous system characterized by loss of dopamine producing neurons in the substantia nigra and the presence of Lewy bodies in the substantia nigra and locus coeruleus. "The inspiration for this article comes from previous studies that demonstrated OTUD3 stabilizes IRP2 to prevent Parkinson's disease." (PMID 40462502, 2025).
colorectal cancer (2 papers, 2024 to 2025). A primary or metastatic malignant neoplasm that affects the colon or rectum. "Over-expressed OTUD3 inhibited YY1 degradation, thereby increasing YY1 protein levels, whereas OTUD3 knockdown or knockout promoted YY1 degradation, thereby decreasing the proliferation of colorectal cancer (CRC)." (PMID 38351178, 2024).
diffuse large B-cell lymphoma (2 papers, 2024 to 2025). "Consistent with this, analogous phenomena were observed in OTUB2 in NSCLC and OTUD3 in diffuse large B-cell lymphoma (DLBCL)." (PMID 40469292, 2025).
influenza (2 papers, 2021 to 2025). An acute viral infection of the respiratory tract, occurring in isolated cases, in epidemics, or in pandemics; it is caused by serologically different strains of viruses (influenzaviruses) designated A, B, and C, has a 3-day incubation period, and usually lasts for 3 to 10 days. "Consistently, intensive antiviral immune response, diminished viral load, and morbidity were observed in OTUD3 knockout mice, and acetyl‐OTUD3 levels are negatively correlated with IFN‐β expression in influenza patients." (PMID 33511009, 2021). "Then, the authors also further analyzed the correlation between the acetylation level of OTUD3 and the expression level of IFN-β in the serum of influenza patients, and they found that the acetylation level of OTUD3 showed a significant negative correlation with the expression level of IFN-β." (PMID 41050073, 2025).
metabolic diseases (2 papers, 2025 to 2026). "OTUD3 then stabilizes SIRT3 via deubiquitination, thereby inhibiting mtDNA oxidation and alleviating steatosis-induced metabolic disorders." (PMID 41640247, 2026).
prostate carcinoma (2 papers, 2019 to 2024). A carcinoma that arises from epithelial cells of the prostate gland. "The ectopic expression of USP11 in PTEN-proficient human prostate cancer cell line DU145 depleted of USP13 or OTUD3 still upregulated PTEN, suggesting that USP11 could be a more potent regulator of PTEN than other DUBs in our assays." (PMID 30733438, 2019).
B-cell lymphoma (1 paper, 2024). "The CCK-8 assay revealed that overexpressing OTUD3 increased B-cell lymphoma cell proliferation, whereas knocking down OTUD3 decreased B-cell lymphoma cell proliferation." (PMID 39097608, 2024).
breast tumors (1 paper, 2019). "As expected, all of PyMT/OTUD3 WT mice spontaneously developed breast tumors at 80–82 days after birth." (PMID 31266968, 2019).
bronchopulmonary dysplasia (1 paper, 2023). Bronchopulmonary dysplasia is a chronic respiratory disease that results from complications related to lung injury during the treatment of infant acute respiratory distress syndrome in low-birth-weight premature infants or from abnormal lung development in older infants. "In Bronchopulmonary dysplasia (BPD) mouse, miR-34c-5p negatively targeted OTUD3 which enhanced proliferation, angiogenesis, and migration in human pulmonary microvascular endothelial cells (HPMECs)." (PMID 37829187, 2023).
cerebral infarction (1 paper, 2025). An ischemic condition of the brain, producing a persistent focal neurological deficit in the area of distribution of the cerebral arteries. "The results of TTC staining experiments showed that OTUD3 knockout aggravated cerebral infarction in MCAO/R mice, and treatment with PLK1‐IN‐6 resulted in a further increase in cerebral infarction volume in mice mediated by OTUD3 deletion." (PMID 40462502, 2025).
colitis (1 paper, 2025). Inflammation of the colon. "The UC-associated Otud3 SNP increases the susceptibility to colitis through cGAS-STING-mediated type I IFN responses due to enhanced K27-linked polyubiquitination of STING." (PMID 41155222, 2025). "Unexpectedly, mice with fibroblast-specific OTUD3 deficiency, created by crossing Pdgfra-cre and Otud3flox/flox mice developed severe DSS-induced colitis." (PMID 41155222, 2025). "Importantly, the development of DSS-induced colitis was markedly attenuated in mice double deficient in STING and OTUD3." (PMID 41155222, 2025). "Collectively, this study utilizing mice with fibroblast-specific OTUD3 deficiency or with UC-associated Otud3 SNP knock-in provided evidence that cGAS-STING-mediated type I IFN responses exacerbate the development of DSS-induced colitis in the absence of OTUD3 or presence of UC-associated Otud3 SNP." (PMID 41155222, 2025).
cryptosporidiosis (1 paper, 2020). Intestinal infection with organisms of the genus Cryptosporidium. "We also identified an association of increased expression of OTUD3 with increased odds of cryptosporidiosis within the first year of life." (PMID 32019797, 2020). "In all tissue-specific models, individuals with predicted increased expression of OTUD3 had an increased risk of cryptosporidiosis within the first year of life (OR, 1.68 to 6.63; P = 8.46 × 10−5 to 8.97 × 10−4)." (PMID 32019797, 2020). "Variants in the gene OTUD3 (OTU deubiquitinase 3) (chr1; position 20208356 to position 20239438) were associated with cryptosporidiosis in 18 different tissue-specific models (P < 0.001)." (PMID 32019797, 2020).
diabetes retinopathy (1 paper, 2022). "The OTUD3 gene rs78466831 was associated with T2DM and may be a biological risk factor of diabetes retinopathy." (PMID 36531510, 2022).
esophageal tumors (1 paper, 2021). "Intriguingly, LYVE-1 staining showed that the number of lymphatic vessels was robustly increased in esophageal tumors with low OTUD3 expression." (PMID 34853315, 2021).
lymph node metastasis (1 paper, 2025). "OTUD3 was significantly down-regulated in heavy smokers compared to non-smoking or normal tissues, and low OTUD3 expression was significantly associated with adverse clinicopathological features, including tumor size, lymph node metastasis, pathological grading, and clinical staging." (PMID 41050073, 2025).
mastitis (1 paper, 2023). Inflammation of breast tissue during lactation or postpartum due to an obstructed duct or infection. "A 200 bp deletion in the Copy number variant regions (CNVRs) of OTUD3 (BTA2) in Holstein-Friesian cows was positively correlated with the incidence of clinical mastitis (CM)." (PMID 37829187, 2023).
metastasis (1 paper, 2020). The spread or migration of cancer cells from one part of the body (where they first appeared) to another. "In contrast, OTUD3 expression was negatively associated with high histological grade (P = 0.009), T2-T3 (>2 cm) tumors (P = 0.007), and lymph node metastasis (P = 0.025)." (PMID 32775453, 2020).
neuroblastoma (1 paper, 2022). Neuroblastoma (NB) is the most common solid, extracranial childhood tumor. "With overexpression of OTUD3, we observed increased IRP2 and TfR1, and decreased ferritin in neuroblastoma cell line SH-SY-5Y." (PMID 35490179, 2022).
ulcerative colitis (1 paper, 2023). An inflammatory bowel disease involving the mucosal surface of the large intestine and rectum. "OTUD3 is a susceptibility gene for Crohn’s disease and ulcerative colitis." (PMID 37829187, 2023). "Previous studies have shown that OTUD3 transcripts are higher in immune tissues and lymphocytes than in CD14-positive cells, suggesting that OTUD3 regulates the immune response, and that mutations in it may be responsible for developing ulcerative colitis." (PMID 37829187, 2023).
tumor (31 papers, 2016 to 2026). "Patient-derived protein data revealed that OTUD3 is highly expressed in DLBCL tumor tissues and is associated with elevated levels of MYL12A and PD-L1." (PMID 39097608, 2024). "Dub OTUD3 played a negative regulatory role in tumor development by inhibiting the K48-linked ubiquitination of PTEN." (PMID 36778143, 2023). "OTUD3 has been identified as a tumor suppressor that is highly associated with tumorigenesis." (PMID 37107185, 2023). "Collectively, two SCCs-associated events (USP7 overexpression and OTUD3 deletion) may cooperate to dampen PTEN tumor suppressor activity." (PMID 32560247, 2020). "To further assess whether OTUD3 is a bona fide tumor suppressor gene, we sought to determine whether loss of OTUD3 expression would induce tumorigenicity." (PMID 31266968, 2019). "OTUD3 was significantly overexpressed in HCC tissues compared with paracancerous tissues and was associated with larger tumor volume, more vascular infiltration, intrahepatic metastasis, worse TNM stage, and lower overall survival." (PMID 41050073, 2025). "In breast cancer, OTUD3 plays a tumour suppressor role by inhibiting the PI3K/AKT signalling pathway through the deubiquitination and stabilization of PTEN, thereby inhibiting tumour progression." (PMID 38658981, 2024). "As a member of DUBs, OTUD3 remove ubiquitin from its substrate, and its role in tumor progression depends on specific substrates." (PMID 38351178, 2024). "In this study, we identified the oncogenic function of the deubiquitinase enzyme OTUD3 in DLBCL, noting increased OTUD3 expression in tumor tissues and its role in promoting DLBCL proliferation and metastasis both in vivo and in vitro." (PMID 39097608, 2024). "These experiments collectively confirmed that OTUD3 can suppress the growth and proliferation of tumor cells." (PMID 38288086, 2023). "If the substrate protein is a tumor suppressor, OTUD3 stabilizes the expression of the substrate protein by deubiquitination and is also a tumor suppressor." (PMID 37829187, 2023). "In summary, our experiments shed light on OTUD3’s intrinsic role in inhibiting tumor initiation and development, proposing a novel mechanism involving KPTN in mTORC1 pathway regulation." (PMID 38288086, 2023). "In particular, OTUD3 has been linked to chemotherapy response, RQCD1 has been linked to tumor growth by uncontrolled activation, and SUCGL2 has been linked to tumor growth in cells with low glucose uptake." (PMID 38102586, 2023). "In this section of the study, we validated, at the cellular level through crystal violet staining and CCK8 cell proliferation assays, that OTUD3 has the capacity to inhibit tumor cell growth and proliferation by downregulating the mTOR signaling pathway." (PMID 38288086, 2023). "Collectively, these data suggest OTUD3’s function in reducing tumor cell proliferation requires the presence of KPTN protein, and the ability of KPTN to inhibit tumor cell proliferation relies on the presence of its ubiquitination site." (PMID 38288086, 2023). "The underlying mechanism is that OTUD3 induces the deubiquitination of glucose-regulated protein 78 (GRP78), and subsequently promotes tumor proliferation and metastasis." (PMID 37251574, 2023). "In BC tissues, OTUD3 knockout can activate Akt pathway, inducing cell transformation and tumor metastasis." (PMID 37251574, 2023). "Ultimately, OTUD3 affects cellular metabolic pool products by downregulating the mTORC1 pathway, significantly inhibiting tumor cell growth and proliferation." (PMID 38288086, 2023).
tumor (continued). "Discussion: Our experiments shed light on an alternative perspective regarding the intrinsic functions of OTUD3 in inhibiting tumor development." (PMID 38288086, 2023). "Consistently, ZFP36 overexpression potently inhibited tumor-induced lymphangiogenesis induced by nicotine or OTUD3 depletion, as indicated by LECs’ migration and tube formation." (PMID 34853315, 2021). "To obtain insight into the function of OTUD3 in facilitating HCC cell proliferation in vitro, we explored the impact of OTUD3 upregulation and downregulation on tumor cell proliferation." (PMID 34380780, 2021). "By employing IVIS to monitor and visualize progression of tumor in mice, we observed that stable OTUD3 interference markedly inhibited lung metastasis." (PMID 34380780, 2021). "Strikingly, we found that ACTN4 upregulation significantly promoted tumor growth, while OTUD3 knockdown effectively inhibited this trend." (PMID 34380780, 2021). "IHC staining with an anti-OTUD3 antibody was performed on 80 pairs of BC tissues and adjacent non-tumor tissues." (PMID 32571254, 2020). "Substantial OTUD3 immunostaining was detected in the adjacent non-tumor tissue samples, whereas little to moderate OTUD3 staining was observed in the BC samples." (PMID 32571254, 2020). "PTEN is a tumor suppressor with a positive relationship with OTUD3 due to depolyubiquitylation, and it is regulated at the posttranscriptional level." (PMID 32775453, 2020). "KrasG12D/WT/OTUD3 KO mice exhibited a dramatically decreased tumor burden, tumor area, which correlated with lower tumor grades compared with that of the KrasG12D/WT/OTUD3 WT mice." (PMID 31266968, 2019). "Collectively, these results demonstrate that OTUD3 facilitated tumor growth and metastasis by regulating GRP78." (PMID 31266968, 2019). "Immunohistochemistry analysis of a tumor microarray (n = 112) showed that about 78.6% of samples with high OTUD3 samples exhibited high GRP78 expression parallelly." (PMID 31266968, 2019). "Consistently, xenograft assays showed that depletion of GRP78 rescued the effects of OTUD3 overexpression and inhibited the tumor development." (PMID 31266968, 2019). "The volume and weight of tumor tissues from PyMT/OTUD3 KO mice were significantly bigger than those of PyMT/OTUD3 WT mice." (PMID 31266968, 2019). "Depletion of OTUD3 in the examined cells all resulted in promotion of tumor growth in xenografted nude mice." (PMID 31266968, 2019). "The PyMT/OTUD3 KO mice showed enhanced rate of cell proliferation, angiogenesis, and dampened rate of cell apoptosis in tumor formation compared with that of the the PyMT/OTUD3 WT mice, as indicated by the Ki67, CD31 and cleaved-Caspase-3 staining." (PMID 31266968, 2019). "Strikingly, the earliest tumor lumps in PyMT/OTUD3 KO mice appears at 70–72 days and more than 50% of the mice developed tumors at 80 days." (PMID 31266968, 2019). "While its roles in HCC have been partially characterized, accumulating evidence reveals that OTUD3 can function as either a tumor suppressor or oncoprotein in a context-dependent manner across various malignancies, including lung, breast, and colorectal cancers." (PMID 40607251, 2025). "For example, in DLBCL, the OTUD3 inhibitor Rupatadine competitively bond to OTUD3 to block PD-L1 deubiquitination, promoting its proteasomal degradation, thereby alleviating PD-1/PD-L1-mediated immune suppression and enhancing anti-tumor T-cell activity." (PMID 40469292, 2025). "Subsequently, we demonstrated that OTUD3 can modulate tumor immunity by stabilizing PD-L1." (PMID 39097608, 2024). "Importantly, we found that OTUD3 acts as an oncogene to accelerate CRC tumor growth by enhancing YY1 stability while YY1 depletion reversed OTUD3 overexpression-induced tumor progression." (PMID 38351178, 2024). "OTUD3 overexpression significantly increased tumor growth and weight in vivo." (PMID 39097608, 2024). "In summary, our study suggests a unique role of OTUD3 in controlling CRC tumor growth." (PMID 38351178, 2024).